ITGB5 (integrin subunit beta 5)
Diseases named in the same sentence as ITGB5 in open-access papers (continued):
Sharing a sentence is not in itself a finding about the gene and the disease.
tumor (66 papers, 2012 to 2025). "ITGB5 encodes the β5-subunit of the integrin, a transmembrane receptor that exclusively pairs the β5 subunit with the αv subunit, promotes tumor progression and is associated with poor prognosis in PDAC." (PMID 40119353, 2025). "We discovered ITGB5 expression upregulated in GC tissues, and the high ITGB5 expression group was positively correlated with advanced tumor stage and positive lymph nodes, which caused a worse prognosis in GC." (PMID 35223869, 2021). "Integrin subunit beta 5 (ITGB5) is a well-known gene associated with tumor invasion and metastasis." (PMID 41425708, 2025). "ITGB5, encoding integrin-β5, was localized to the plasma membrane and mitochondria, which was supposed to be associated with the initiation and progression of the tumor by mediating links between the ECM and cells." (PMID 35223869, 2021). "We used the TIMER algorithm to investigate whether ITGB5 expression is associated with immune infiltration in GC and the abundance of six tumor-infiltrating immune cells (B cells, CD4+ T cells, CD8+ T cells, macrophages, neutrophils, and dendritic cells)." (PMID 35223869, 2021). "Besides, ITGB5, encoding integrin-β5, was thought to be involved in the regulation of tumor initiation and progression by mediating links between cells and ECM." (PMID 33178362, 2020). "The levels of ITGAV, ITGB3 and ITGB5 were significantly higher in GBM samples than in non-tumor specimens." (PMID 40281508, 2025). "Pathogenic IgG targeting glycosylated membrane HSPA4 selectively promotes lymph node metastasis and activates the downstream Src/NF-κB in ITGB5 and tumor cells for CXCR4/SDF1α axis-mediated metastasis." (PMID 41357192, 2025). "In this study, we identified the POSTN-ITGAV/ITGB5 axis as a tumor-promoting signaling axis that mediates crosstalk between ECM-remodeling fibroblasts and EMT-associated epithelial cells." (PMID 40520021, 2025). "Here, we provide evidence that NAT10 promotes the expression of ITGB5, a vital receptor in the focal adhesion pathway, thereby activating this signaling pathway to promote tumor invasion." (PMID 40119353, 2025). "The expression levels of integrin subunit alpha V (ITGAV) and integrin subunit beta 5 (ITGB5) were significantly increased in tumor tissues and correlated with poor prognosis of HCC patients." (PMID 41018265, 2025). "Mechanistically, POSTN interacts with integrin ITGAV/ITGB5 on tumor cells, activating the PI3K/AKT/β-catenin pathway and promoting epithelial-mesenchymal transition (EMT) phenotype." (PMID 40520021, 2025). "Identification of the POSTN-ITGA5/ITGB5 signaling axis and its role in PDAC progression through the PI3K/AKT/β-catenin pathway elucidates key mechanisms underlying tumor aggressiveness and poor prognosis." (PMID 40520021, 2025). "Previous studies have reported that upregulated expression of ITGB5 in tumor cells promote metastasis in PDAC." (PMID 40119353, 2025). "Ligand‒receptor analysis revealed that azvudine predominantly regulated signal transduction from tumor CD4+ T cells to other immune cells through SPP1-(ITGAV + ITGB5) and SPP1-(ITGAV + ITGB1), as well as COL1A1-(ITGA9 + ITGB1), COL1A1-CD44, and COL1A1-SDC4." (PMID 39819859, 2025). "The level of ITGB5, a glycoprotein involved in facilitating cell migration and angiogenesis, was also highly expressed in these tumours (p < 0.05)." (PMID 38786043, 2024). "Further analysis of cell‐cell communications via ligand‐receptor interactions unveiled robust communication between the subset of IL32‐positive pericytes and tumor cells expressing β5‐integrin (gene name: ITGB5)." (PMID 39435643, 2024). "ITGB5 promoted the FAK axis to stimulate tumor cell glycolysis while suppressed CDDP anti-tumor properties." (PMID 38741195, 2024). "Among stromal fibroblast cells, ITGAV, ITGA1, ITGB1, and ITGB5 were significantly upregulated following IO and, notably, isolated tumor cells found in the stroma showed upregulation of B2M, VIM, ITGA5, ITGB2, and ITGA3." (PMID 39639369, 2024).
tumor (continued). "ITGB5 depletion reduced tumor growth, survival, proliferation, migration, invasion, and angiogenesis." (PMID 37834160, 2023). "We found that the POSTN pathway (POSTN-ITGAV/ITGB5) was enhanced from GCTB tumor cells to TAMs after DMAB treatment." (PMID 36172351, 2022). "ITGB5 depletion significantly inhibited xenograft tumor growth in both PANC-1 and BXPC3 by recording tumor volume and tumor weight." (PMID 36249018, 2022). "ITGB5 not only regulates the biological behavior of cancer through the tumor microenvironment but also plays an important role in stemness and chemotherapy resistance in cancer cells." (PMID 35699863, 2022). "When ITGB5 was downregulated, Ki67 protein expression was inhibited, which further supported the results of in vitro experiments that ITGB5 depletion inhibited tumor proliferation." (PMID 36249018, 2022). "Along with this, ITGB5 not only promotes migration but also invasion, and has been reported to affect immune response and angiogenesis within the tumor microenvironment." (PMID 34680783, 2021). "The total tumor-associated macrophages were positively correlated with the level of ITGB5, which indicates higher M2 macrophage infiltration, thus supporting the view that ITGB5 may play a vital role in the progression of GC via promoting M2 macrophage polarization and inhibiting antitumor immunity." (PMID 35223869, 2021). "The results were displayed a heatmap, which showed the expression levels of P3H1, SPP1, MMP1, LGALS1, and ITGB5 in tumor tissues and normal tissues." (PMID 32951492, 2020). "The results showed that CD8+ T cell, NK cell, fibroblast, B cell, monocyte, and myeloid dendritic cell numbers were positively associated with ITGB5 expression, providing further evidence for the regulatory role of ITGB5 in the local tumor microenvironment." (PMID 31616629, 2019). "ITGB5 was the only gene correlated with tumor purity and immune and stromal scores in CGGA and TCGA datasets (r > 0.45 or < -0.45)." (PMID 31616629, 2019). "This investigation intended to evaluate the association between FN-1, ITGA-3, ITGB-5, MMP-2, and MMP-9 gene and protein expression levels in tumor tissue with clinical and histopathological neoplastic parameters of cancer dissemination." (PMID 24737953, 2014). "High ITGB5 expression in PC tissues promotes tumor cell invasion and migration." (PMID 41235257, 2025). "ITGB5 significantly suppressed the anti-tumor properties of CDDP." (PMID 38741195, 2024). "ITGB5 facilitated tumor cell glycolysis by promoting the FAK/p-FAK axis." (PMID 38741195, 2024). "The expression of ITGAV, ITGB3, and ITGB5 in EwS was comparable to other tumor entities." (PMID 38318175, 2024). "Most genes exhibited high expression in tumor cells, except for ITGB5, which may be due to the limited sample size." (PMID 36968601, 2023). "Many recent studies have reported the potential role and mechanisms of ITGB5 in tumor progression." (PMID 36249018, 2022). "Integrin beta 5 (ITGB5) is demonstrated to be a potent tumor promoter in several carcinomas." (PMID 36249018, 2022). "As one of the mesenchymal markers, ITGB5 may serve as an indicator of the metastatic potential and tumor chemosensitivity." (PMID 34908921, 2021). "Finally, the correlation of ITGB5 expression with immune infiltrates in GC is clarified by Tumor IMmune Estimation Resource (TIMER)." (PMID 35223869, 2021). "Considering ITGB5 expressed in normal tissue and non-tumor cells, further study is needed to investigate whether systematic blockade of ITGB5 may lead to potential side effects, like immunosuppression." (PMID 31616629, 2019). "We show that ITGB5 expression is positively correlated with the number of monocyte lineage cells, which may reflect the mechanism by which ITGB5 regulates the tumor microenvironment." (PMID 31616629, 2019). "However, the combination with 5-FU and foretinib markedly inhibited tumor growth, which was further suppressed when combined with 5-FU, foretinib and ITGB5-ab." (PMID 30782177, 2019).
tumor (continued). "However, the role of ITGB5 in the tumor microenvironment is not fully understood." (PMID 31616629, 2019). "The ITGA-3 and ITGB-5 gene expression levels in the tumor tissue as determined using RT-PCR were not considered significant when analyzed with regard to the different measures of tumor dissemination outcome, except for those related to TNM staging and cell differentiation degree." (PMID 24737953, 2014). "Compared with NAT10-KD cells, the invasion of tumor cells toward DRG and tumor proliferation were significantly increased when ITGB5 was overexpressed." (PMID 40119353, 2025). "While dabrafenib directly inhibits BRAF activity, HT induced a broader suppression of oncogenic proteins involved in tumor-stroma crosstalk and angiogenesis, including VEGFR-2, WIF-1, ITGB5, and ERBB2/3/4." (PMID 40725203, 2025). "This is consistent with reports that ITGA11 expression in CAF is required for CAF-induced tumor cell invasion and that CAF deposit ECM tracks enriched with the YAP1 target gene and C3 marker ITGB5, which serve as guidance cues for cancer cell migration." (PMID 41327318, 2025). "Specifically, SPP1 released from tumor cells interacted with CD44, ITGAV, ITGA5, ITGB1, and ITGB5 on immune clusters." (PMID 39505867, 2024). "SPP1 bound with integrins such as ITGB1 and ITGB5, implying the role of SPP1 in integrin signaling between fibroblasts, macrophages, and tumor cells that lead to EMT and cell-adhesion to the ECM." (PMID 39075108, 2024). "Seven genes of the prognostic model (COPA, GPX7, ITGB5, MATN3, MCM7, MMP1, and SPP1) have been validated to be related to tumor progression, whereas the remaining three genes, BNDF, GADD45B, and LOX, need to be further analyzed." (PMID 35699863, 2022). "The results showed that ITGB1 (4/10), ITGB3 (6/10), ITGB5 (6/10), and ITGB6 (5/10) protein levels were increased in tumour tissues compared to adjacent tissues." (PMID 34709754, 2021). "Among the integrin β‐subunits, ITGB1, ITGB2, ITGB4, ITGB5, ITGB6, ITGB7, and ITGB8 were highly expressed in tumour tissues compared with normal tissues." (PMID 34709754, 2021). "The reduced migration observed on fibronectin, for example, hints at tumor cell-ECM interaction regulated by Itgb3 and/or Itgb5." (PMID 32525899, 2020). "Integrin beta 5 (ITGB5) is thought to be involved in intercellular signal transduction and regulation of tumor initiation and progression." (PMID 31616629, 2019). "We found that knockdown of CDCP1 or ITGB5 slows the growth of cells addicted to RAS signaling, supporting the idea that oncogenic RAS promotes the expression of these proteins to enable tumor cell growth." (PMID 29359686, 2018). "Furthermore, ITGB5 enhances the EMT process and the Wnt/β-catenin signaling pathway, thereby promoting tumor growth and metastasis." (PMID 41425708, 2025). "In addition, PDFs secreted higher amounts of ITGB5 and SPARC, both of which are known to facilitate EMT and ECM remodeling, as well as Gal‐2, which contributes to tumor immunosuppression." (PMID 40411295, 2025). "rTAM also expressed distinct integrin transcripts, including Itga6, Itgb1, and Itgb5, which bind ECM components including laminin and collagen, and may facilitate interaction at the tumour-normal interface." (PMID 40523200, 2025). "Spatial validation through immunofluorescence in tissue sections from four patients in the PUCH-PDAC cohort showed significant co-localization of POSTN and integrin β5 on tumor cell membranes, providing in situ evidence for the functional relevance of the POSTN-ITGAV/ITGB5 axis in PDAC." (PMID 40520021, 2025). "Thus, results for SOCS3 and ITGB5 verified an anti-inflammatory state; results for SOCS3 and AHSP verified a state of enhanced energy efficiency, and the result for CXCL10 (tumor suppressor) verified a higher defense response in the meditation group." (PMID 33804348, 2021).
tumor (continued). "After adjustment by tumor purity, we found ITGA1/A5/A8/A11/AD/AV and ITGB1 showed weakly correlation with macrophage markers in OC, ITGA5/A11 and ITGB5 weakly correlated with Treg markers, ITGAD and ITGB6 showed weakly correlation with natural killer cells markers." (PMID 32765584, 2020). "In addition, previous studies suggested that ITGB5 and IL18 are related to tumor invasiveness, whereas CXCL1 and SEMA4F are associated with cell proliferation." (PMID 31118022, 2019). "In contrast, the expression of ITGA2B was the opposite, and significantly negative correlation with ITGA5 and ITGB5 in tumor tissue." (PMID 29100351, 2017). "The 38 tumor cell lines expressed the genes encoding αv (ITGAV, expression signal above 10 in most cases, data not shown), and β5 integrin chains (ITGB5)." (PMID 23977342, 2013). "To further clarify whether inhibition of ITGB5 and activation of TIMP1 and TMEM176B affect tumor cell migration, we also used dCas9-KRAB-mediated CRISPRi technology to knock down ITGB5 expression, and used dCas9-VPR-mediated CRISPRa technology to induce TIMP1 and TMEM176B activation." (PMID 34109215, 2021). "In order to further clarify whether ITGB5 is a proto-oncogene and whether TIMP1 and TMEM176B are tumor suppressor genes, we used dCas9-KRAB-mediated CRISPRi technology to knock down the expression of ITGB5, and used dCas9-VPR-mediated CRISPRa technology to activate TIMP1 and TMEM176B expression." (PMID 34109215, 2021). "To further clarify whether knockdown of ITGB5 and activation of TIMP1 and TMEM176B expression affect tumor cell invasion, we used dCas9-KRAB-mediated CRISPRi to knock down ITGB5 expression, and used dCas9-VPR-mediated CRISPRa to activate TIMP1 and TMEM176B expression." (PMID 34109215, 2021). "Moreover, the prognostic signature based on ITGB1, ITGB4, ITGB5 and ITGB6 may facilitate clinicians to identify more aggressive and immunosuppressive tumours and make more individually appropriate therapeutic decisions." (PMID 33073486, 2020). "Of importance, not all the EV protein cargo reflected the transcriptional effects induced by TGF-β, as noted for NOG, ITGB5 and MMP10, suggesting that sorting of different cargo proteins into tumor-derived EVs does not strictly follow the abundance of the respective mRNA." (PMID 39910665, 2025). "Co-expression analysis indicated that ITGA5 mRNA expression had a significantly positive correlation with ITGB5 (r=0.32, P<0.001) in tumor tissue, whereas ITGA2B had a significantly negative correlation with ITGA5 (r=-0.142, P =0.035) and ITGB5 (r=-0.34, P <0.001), respectively." (PMID 29100351, 2017).
cancer (32 papers, 2011 to 2025). A tumor composed of atypical neoplastic, often pleomorphic cells that invade other tissues. "The ITGB5 gene encoding integrinβ5 has been frequently found to be overexpressed in the progression and invasion of various types of human cancers." (PMID 40106490, 2025). "ITGB5 has been implicated in numerous physiological and pathological processes, including embryonic development, wound healing, cancer metastasis, and inflammation." (PMID 40074694, 2025). "ITGB5, associated with focal adhesion, immune suppression, and signaling pathways critical in cancer progression and poor survival outcomes in various cancers, is less studied in CC but is reported to activate the focal adhesion pathway, inducing cisplatin resistance in CC cells." (PMID 38835778, 2024). "Importantly, genes associated with cancer progression (i.e., Itgb2, Itgb5, paxillin, fyn) displayed increased expression, whereas those thought to suppress progression (i.e., vinculin, gravin) exhibited decreased levels of expression compared to MOSE-E cells." (PMID 21390237, 2011). "Furthermore, genes encoding proteins for cell adhesion, such as GJA1 and ITGB5, were downregulated, suggesting a loss of cell-to-cell communication, which may contribute to cancer progression." (PMID 40056285, 2025). "Further analysis of ligand-receptor pairs revealed that VTN-(ITGAV + ITGB5), SEMA4D-PLXNB2, GAS6-TYRO3, and FN1-(ITGA3 + ITGB1) were more prevalent in high-risk cancer cells." (PMID 41034991, 2025). "These validation screens suggested that in addition to those targeting ITGAV, the sgRNAs targeting ITGB5 were strongly depleted in both cancer cell models." (PMID 38316881, 2024). "Although YAP, TAZ, and ITGB5 are downregulated in YAPoff cancers, the UNC5 family show varying levels depending on the paralog." (PMID 39172021, 2024). "While no specific studies have investigated ITGB5’s role in MS, data from the literature indicate a positive correlation of ITGB5 with immune infiltration in cancer." (PMID 38542346, 2024). "Our results identified ITGAV (integrin αV) and its heterodimer partner ITGB5 (integrin β5) as the essential integrin α/β pair for cancer cell expansion." (PMID 38316881, 2024). "ITGB5 is upregulated in numerous cancer types including PAAD (Ntumor = 179, Nnormal = 171) compared to normal samples." (PMID 36249018, 2022). "ITGB5, TIMP1, and TMEM176B can be used as molecular diagnostic targets or therapeutic targets in the future, as their combination is useful for cancer treatment." (PMID 34109215, 2021). "HSPA4 targeting IgG activated the HSPA4-binding protein ITGB5 and the downstream Src/NF-κB pathway in cancer cells to promote CXCR4/SDF1α-axis-mediated cancer metastasis." (PMID 32746880, 2020). "In a former study, ITGB5 was found to be differentially expressed in the NCI-60 cancer cell panel, thus suggesting that adhesion molecules could have a major role in radiosensitivity." (PMID 39202425, 2024). "Firstly, we analyzed ITGB5 expression in cancers by the GEPIA database." (PMID 36249018, 2022). "Along with the existing evidence, the results of our study confirm that ITGB5 might act a critical role in the immune mechanism of cancer." (PMID 35223869, 2021). "Although it suppresses cancer invasion through reaction on ITGB5, Panax ginseng may also stimulate bone marrow blast by activating CTGF." (PMID 28454110, 2017). "Additionally, SPP1 as a ligand could induce communications of pan T‐cell subtypes to cancer cells specifically in BM or to senescent cancer cells via adhesive receptors ITGAV_ITGB1, ITGAV_ITGB5 and ITGAV_ITGB6." (PMID 39231761, 2025). "Meanwhile, other cell-cell adhesion-related molecules, such as laminins (LAMA4, LAMA5, LAMB1, LAMB2 and LAMC2) and integrins (ITGA5, ITGA5, ITGB5, ITGA11 and ITGBL1), are elevated in cancer tissues." (PMID 22905095, 2012).
cancer (continued). "A logistic regression model, using 5 proteins (ITGB5, TGF-α, TLR3, WIF-1, and ERBB3) with highest AUC values, demonstrated good predictive performance for prognosis of CC patients undergoing immunotherapy and showed potential across different cancer types." (PMID 38835778, 2024). "Among these, integrin beta-5 (ITGB5) and its partner integrin alpha-V (ITGAV) were recognized, as they mediate cell–matrix adhesion and play a procancer role in YAPon cancers, while exhibiting an opposing effect by suppressing cell growth in YAPoff cancers." (PMID 38067201, 2023). "We found that ITGB5 promotes cancer, while TIMP1 and TMEM176B suppress cancer." (PMID 34109215, 2021). "ITGB5, TIMP1, and TMEM176B are abnormally expressed in several human cancers." (PMID 34109215, 2021). "Among them, ITGB5 is highly expressed cancers, TIMP1, and TMEM176B are lowly expressed in cancers." (PMID 34109215, 2021). "Integrins, including TGA5, ITGA5, ITGB5, ITGA11, and ITGBL1 elevated in cancer tissues." (PMID 29843204, 2019). "However, the increased expression of GADD45B, ITGB5, MMP1, and BNDF was correlated with a decreased chemotherapy resistance of cancer cells to mithramycin, tramrtinib, ARRY-162, dabrafenib, selumetinib, vemurafenib, nilotinib, coimetinib, cyclophosphamide, oxaliplatin, and tamoxifen." (PMID 35699863, 2022).